TRBV10-2 (T cell receptor beta variable 10-2)
Description:
V region of the variable domain of T cell receptor (TR) beta chain that participates in the antigen recognition. Alpha-beta T cell receptors are antigen specific receptors which are essential to the immune response and are present on the cell surface of T lymphocytes. Recognize peptide-major histocompatibility (MH) (pMH) complexes that are displayed by antigen presenting cells (APC), a prerequisite for efficient T cell adaptive immunity against pathogens. Binding of alpha-beta TR to pMH complex initiates TR-CD3 clustering on the cell surface and intracellular activation of LCK that phosphorylates the ITAM motifs of CD3G, CD3D, CD3E and CD247 enabling the recruitment of ZAP70. In turn ZAP70 phosphorylates LAT, which recruits numerous signaling molecules to form the LAT signalosome. The LAT signalosome propagates signal branching to three major signaling pathways, the calcium, the mitogen-activated protein kinase (MAPK) kinase and the nuclear factor NF-kappa-B (NF-kB) pathways, leading to the mobilization of transcription factors that are critical for gene expression and essential for T cell growth and differentiation. The T cell repertoire is generated in the thymus, by V-(D)-J rearrangement. This repertoire is then shaped by intrathymic selection events to generate a peripheral T cell pool of self-MH restricted, non-autoaggressive T cells. Post-thymic interaction of alpha-beta TR with the pMH complexes shapes TR structural and functional avidity.
Synonyms: TRBV102; TCRBV10S2; TCRBV12S3
Gene: T-cell receptor variable (V) gene on chromosome 7 (142,424,965 to 142,425,465, forward strand). Ensembl gene ENSG00000229769.
Subcellular location: Cell membrane
Gene Ontology:
Biological process: cell surface receptor signaling pathway
Cellular component: plasma membrane
Homologues: Orthologues: mouse Trbv13-3 (62% identical), mouse Trbv13-2 (59% identical), mouse Trbv13-1 (58% identical). Paralogues in human: TRBV10-1 (82% identical), TRBV10-3 (79% identical), TRBV6-4 (62% identical), TRBV6-7 (62% identical), TRBV6-5 (61% identical), TRBV6-6 (61% identical), TRBV6-8 (61% identical), TRBV27 (59% identical), TRBV6-1 (58% identical), TRBV6-2 (58% identical), TRBV28 (54% identical), TRBV24-1 (52% identical), and 39 more.